YIPF6 (Yip1 domain family member 6)
Description:
May be required for stable YIPF1 and YIPF2 protein expression.
Synonyms: MGC21416; FinGER6; Yip4; YIPFalpha3
Tractability: Antibody: UniProt predicts a signal peptide or a membrane-spanning region. PROTAC: ubiquitination databases record sites on it; its protein half-life has been measured.
Gene: Protein-coding gene on chromosome X (68,498,562 to 68,537,282, forward strand). Ensembl gene ENSG00000181704.
Subcellular location: Golgi apparatus membrane
Subcellular location (Human Protein Atlas): Vesicles
Pathways (Reactome):
Vesicle-mediated transport: Golgi Associated Vesicle Biogenesis
Gene Ontology:
Molecular function: protein binding; identical protein binding
Biological process: endoplasmic reticulum to Golgi vesicle-mediated transport
Cellular component: endoplasmic reticulum; Golgi medial cisterna; Golgi membrane; Golgi trans cisterna; trans-Golgi network; cis-Golgi network; COPII-coated ER to Golgi transport vesicle; endomembrane system; membrane
Homologues: Orthologues: chimpanzee YIPF6 (100% identical), pig YIPF6 (95% identical), guinea pig YIPF6 (94% identical), macaque YIPF6 (94% identical), dog YIPF6 (90% identical), mouse Yipf6 (83% identical), rat Yipf6 (81% identical), rabbit YIPF6 (77% identical), tropical clawed frog yipf6 (75% identical), zebrafish yipf6 (69% identical), Drosophila melanogaster CG3652 (47% identical), Caenorhabditis elegans W02D9.2 (44% identical). Paralogues in human: YIPF5 (24% identical), YIPF7 (23% identical), YIPF4 (21% identical).
Diseases named in the same sentence as YIPF6 in open-access papers:
YIPF6 is named in the same sentence as 4 diseases in open-access papers, as found by Europe PMC text mining. Sharing a sentence is not in itself a finding about the gene and the disease. The quoted sentences say what the papers report.
prostate carcinoma (3 papers, 2019 to 2023). A carcinoma that arises from epithelial cells of the prostate gland. "YIPF6 has been associated with prostate cancer, and amplification and overexpression of YIPF6 protein has been posited to indirectly stimulate tumor progression." (PMID 30913233, 2019). "Next, YIPF6 is significantly overexpressed in castration-resistant prostate cancer; however, in the same disease BET1’s lower expression is associated with early relapse." (PMID 36979661, 2023).
colitis (1 paper, 2017). Inflammation of the colon. "Mice with null mutated Yipf6 were extremely sensitive to dextran sodium sulfate (DSS)-induced colitis." (PMID 28045058, 2017).
cancer (1 paper, 2019). A tumor composed of atypical neoplastic, often pleomorphic cells that invade other tissues. "YIPF6, TMEM9, and PSME3 have been associated with cancer and SPIRE1 reportedly contributes to metastatic potential." (PMID 30913233, 2019).
YIPF6 also shares sentences with these, for which no sentence is quoted: tumor (2 papers).